CREB3L3 (cAMP responsive element binding protein 3 like 3)
Description:
Transcription factor that may act during endoplasmic reticulum stress by activating unfolded protein response target genes. Activated in response to cAMP stimulation. In vitro, binds to the cAMP response element (CRE) and box-B element. Activates transcription through box-B element. Activates transcription through CRE (By similarity). May function synergistically with ATF6. In acute inflammatory response, may activate expression of acute phase response (APR) genes. May be involved in growth suppression. Regulates FGF21 transcription (By similarity). Plays a crucial role in the regulation of triglyceride metabolism and is required for the maintenance of normal plasma triglyceride concentrations.
Synonyms: CREBH; HYST1481; CREB-H; HYTG2
Tractability: Antibody: UniProt predicts a signal peptide or a membrane-spanning region. PROTAC: UniProt records ubiquitination sites on it; ubiquitination databases record sites on it.
Gene: Protein-coding gene on chromosome 19 (4,153,621 to 4,173,057, forward strand). Ensembl gene ENSG00000060566.
Subcellular location: Endoplasmic reticulum membrane; Nucleus (Processed cyclic AMP-responsive element-binding protein 3-like protein 3)
Pathways (Reactome):
Cellular responses to stimuli: CREB3 factors activate genes
Transport of small molecules: Assembly of active LPL and LIPC lipase complexes
Gene Ontology:
Molecular function: DNA-binding transcription activator activity, RNA polymerase II-specific; identical protein binding; protein binding; protein heterodimerization activity; protein homodimerization activity; RNA polymerase II transcription regulatory region sequence-specific DNA binding; transcription cis-regulatory region binding; DNA-binding transcription factor activity, RNA polymerase II-specific; RNA polymerase II cis-regulatory region sequence-specific DNA binding; DNA-binding transcription factor activity
Biological process: positive regulation of transcription by RNA polymerase II; response to endoplasmic reticulum stress; positive regulation of acute inflammatory response; regulation of transcription by RNA polymerase II; regulation of DNA-templated transcription
Cellular component: endoplasmic reticulum; nucleus; chromatin; cytosol; endoplasmic reticulum membrane; Golgi membrane; membrane; nucleoplasm
Genetic constraint (gnomAD): Loss-of-function variants: 34 observed, 39.17 expected, observed/expected ratio (o/e) 0.87, 90% interval 0.66 to 1.15. The upper end of that interval is the gene's LOEUF score, 1.15, which puts it in group 5 of 6, group 1 being the genes least tolerant of losing a copy. Missense variants: 524 observed, 561.94 expected, observed/expected ratio (o/e) 0.93, 90% interval 0.87 to 1. Synonymous variants: 256 observed, 245.48 expected, observed/expected ratio (o/e) 1.04, 90% interval 0.94 to 1.16.
Homologues: Orthologues: chimpanzee CREB3L3 (99% identical), macaque CREB3L3 (93% identical), pig CREB3L3 (76% identical), dog CREB3L3 (74% identical), mouse Creb3l3 (71% identical), guinea pig CREB3L3 (64% identical), rat Creb3l3 (56% identical), zebrafish creb3l3a (40% identical), zebrafish creb3l3b (34% identical), Drosophila melanogaster CrebA (17% identical), Caenorhabditis elegans crh-2 (16% identical), Caenorhabditis elegans atf-6 (14% identical), and 3 more. Paralogues in human: CREB3L4 (31% identical), CREB3 (26% identical), CREB3L1 (25% identical), CREB3L2 (24% identical), ATF6B (20% identical), ATF6 (18% identical), CREB1 (12% identical), CREM (12% identical), ATF1 (10% identical).
Diseases named in the same sentence as CREB3L3 in open-access papers:
CREB3L3 is named in the same sentence as 40 diseases in open-access papers, as found by Europe PMC text mining. Sharing a sentence is not in itself a finding about the gene and the disease. The quoted sentences say what the papers report.
hypertriglyceridemia (14 papers, 2013 to 2025). A laboratory test result indicating elevated triglyceride concentration in the blood. "The transcription factor CREB-H (CREB3L3) is required for the maintenance of normal plasma TG concentrations, and loss-of-function mutations in the CREB3L3 gene are associated with severe hypertriglyceridemia in humans." (PMID 32849290, 2020). "Humans with mutations in CREB3L3 exhibit hypertriglyceridemia and hypercholesterolemia." (PMID 40449732, 2025). "Interestingly, in both humans and mice, individuals with mutations in Creb3L3/CrebH, one of the Creb3 family members, exhibit hypertriglyceridemia (HTG) thus linking this transcription factor to lipid metabolism." (PMID 31293620, 2019). "Furthermore, multiple nonsynonymous mutations in CREB3L3 are associated with extreme hypertriglyceridemia, suggesting a pivotal role of CREBH in human TG metabolism." (PMID 28860159, 2017). "Previous studies of mice null for CREB3L3 (whole body) indicate that they develop and reproduce normally yet have severe hypercholesterolemia and hypertriglyceridemia." (PMID 40449732, 2025). "Further, overexpression of Creb3l3 in hepatocytes improves hypertriglyceridemia and hypercholesterolemia phenotypes in wild-type mouse studies." (PMID 40449732, 2025). "The hypertriglyceridemia in CREB3L3−/− mice was improved by the simultaneous ablation of PPARα, suggesting functional antagonism between PPARα and CREB3L3 in plasma triglyceride regulation." (PMID 30866796, 2019). "For instance, CREB3L3 and CDX1 are not assigned any disorders on OMIM but are on the ‘severe hypertriglyceridaemia’ panel and ‘nonsyndromic familial congenital anorectal malformations’ panel, respectively, in the Genomics England PanelApp." (PMID 33836063, 2021).
Hepatic steatosis (13 papers, 2015 to 2025). Steatosis is a term used to denote lipid accumulation within hepatocytes. "Consistently, the deficiency of Creb3l3 developed severe hepatic steatosis." (PMID 27982131, 2016). "Furthermore, as KD-fed Creb3l3−/− mice exhibited severe fatty liver, activating inflammation, CREB3L3 could be a therapeutic target for NAFLD." (PMID 27982131, 2016). "CREB3L3 is a transcription factor that may act during endoplasmic reticulum stress by activating unfolded protein response target genes, and it promotes lipid droplet growth and hepatic steatosis." (PMID 26731332, 2016). "Interestingly, FGF21 overexpression partially restored the expression of PPARα and its target genes, Acox1, Hmgcs2 and Cpt1a in Creb3l3−/− mice, which might have helped to improve the hepatic steatosis." (PMID 27301791, 2016). "Interestingly, overexpression of FGF21 ameliorated hepatic steatosis and NASH symptoms of KD-fed Creb3l3−/− mice, suggesting that FGF21 is one of the major CREBH targets that help alleviate steatosis and NASH." (PMID 27301791, 2016). "Taken together, these data suggest that the severe fasting-induced hepatic steatosis in Creb3l3−/− mice is primarily due to increased adipose tissue lipolysis, whereas de novo lipogenesis, VLDL production, and fatty acid oxidation were unaffected in Creb3l3−/− mice." (PMID 27301791, 2016). "In the current study, we systematically explored the mechanisms by which CREBH regulates hepatic TG content, and demonstrated that the increased NEFA delivery from adipose tissue to the liver is primarily responsible for the worsened hepatic steatosis in Creb3l3−/− mice." (PMID 27301791, 2016).
hepatoma (12 papers, 2013 to 2025). "For instance, CREB3L3 was associated with the proliferation and prognosis of hepatocellular carcinoma by regulating PI3K/Akt and AMPK signaling pathways." (PMID 36120545, 2022). "A previous study has shown that loss of CREB3L3 function in hepatocellular carcinoma might contribute to the occurrence and/or progression of cancer." (PMID 34966575, 2021). "CREB3L3 overexpression suppresses proliferation in hepatoma cells and has been described to be downregulated in hepatocellular carcinoma." (PMID 32817744, 2020).
hyperlipidemia (10 papers, 2016 to 2025). "Future studies using intestine-specific Creb3l3 knockout mice may demonstrate CREB3L3 as a therapeutic target for improving hyperlipidemia." (PMID 27291420, 2016). "During fasting, dependency of ketogenesis on CREB3L3 is lesser extents than Ppara−/− mice suggesting importance of adipose PPARα for supply of FFA and hyperlipidemia in Creb3l3−/− mice." (PMID 27982131, 2016). "The liver-specific knockout of Creb3l3 in mice exhibits hyperlipidemia and nonalcoholic steatohepatitis, while the intestine-specific Creb3l3 knockout mice were not hyperlipidemic but did show a modest increase in the amount of total body fat." (PMID 40449732, 2025).
Obesity (10 papers, 2013 to 2025). Accumulation of substantial excess body fat. "Given its ability to modulate body weight during obesity, adipose CREB3L3 could offer a potential weight loss target to help curb the obesity epidemic." (PMID 34588527, 2021). "Our results demonstrate the key role that CREB3L3 plays in modulating body weight and preventing pathological changes in both subcutaneous and visceral fat during obesity." (PMID 34588527, 2021). "The resistance of sOE mice to diet-induced obesity, when coupled with enhanced diet-induced obesity in the fKO mice, demonstrated the important role that CREB3L3 plays in body weight and fat mass regulation." (PMID 34588527, 2021). "Strikingly, increased expression of CREB3L3 reduced body weight gain in mice with diet-induced obesity." (PMID 34588527, 2021). "In our fat-specific knockout mice, we found that adipose ablation of CREB3L3 promotes diet-induced obesity." (PMID 34588527, 2021). "Together, through its contributions to regulating both adiposity and visceral inflammation, we have identified the importance of CREB3L3 in the transcriptional control of adipose behavior during obesity." (PMID 34588527, 2021). "These mice were resistant to diet-induced obesity, further demonstrating the importance of CREB3L3 in body weight regulation." (PMID 34588527, 2021). "Conversely, inguinal fat CREB3L3 overexpression deterred diet-induced obesity and ameliorated metabolic dysfunction." (PMID 34588527, 2021). "In this study, we discovered that adipose expression of CREB3L3 is modulated by obesity." (PMID 34588527, 2021). "In addition to being present in the adipose tissue, we also found that CREB3L3 is selectively downregulated in the subcutaneous fat during obesity, while the expression in the visceral fat is largely unchanged." (PMID 34588527, 2021). "Similarly, this specific downregulation of CREB3L3 was observed in the iWAT of a genetic model of obesity (ob/ob), and was also seen at the protein level, as evidenced by the reduced abundance of CREB3L3 in the iWAT of C57BL/6J mice following high-fat feeding." (PMID 34588527, 2021). "Given the preserved browning potential of the iWAT in response to cold and the temperature-dependence of the obesity-promoting phenotype of the fKO mouse, it appears that altered brown fat metabolism is the main contributor to the obesigenic effect of adipose CREB3L3 ablation." (PMID 34588527, 2021). "Additionally, the enhanced pro-inflammation cytokine expression within the epididymal fat of the fKO mice during obesity suggests that CREB3L3 could play a role in limiting the extent of inflammation within obese visceral fat." (PMID 34588527, 2021).
dyslipidemia (6 papers, 2016 to 2025). "No previous research was found associating the presence of the risk variants found in CELSR2 and CREB3L3 with alterations in the lipid profile or risk of suffering from dyslipidemia." (PMID 37065472, 2023). "According, CREB3L3 may contribute to the pathogenesis of metabolic syndrome through its role in regulating enterohepatic circulation." (PMID 27291420, 2016).
Insulin resistance (5 papers, 2019 to 2023). Increased resistance towards insulin, that is, diminished effectiveness of insulin in reducing blood glucose levels. "Fat-specific ablation of CREB3L3 enhanced weight gain and insulin resistance following high-fat feeding, as fat-specific knockout mice expended less energy and possessed more inflammatory adipose tissue." (PMID 34588527, 2021).
steatosis (3 papers, 2015 to 2023). Increased lipid within the cytoplasm of cells. "For example, it is unlikely that decreased expression of lipogenic transcription factors and enzymes contributed to severe steatosis in Creb3l3−/− mice." (PMID 27301791, 2016). "Specifically, females showed an increase in pparg and srebp1c, two genes that are known to be involved in activation and de novo lipogenesis, as well as the hepatic synthesis of fatty acid, and a decrease in creb3l3, which has a protective role with regards to the development of steatosis." (PMID 26183212, 2015).
osteoporosis (2 papers, 2021 to 2023). A condition of reduced bone mass, with decreased cortical thickness and a decrease in the number and size of the trabeculae of cancellous bone (but normal chemical composition), resulting in increased fracture incidence. "Inhibition of ER stress, however, reduced the expression of osteoclast-related genes and CREB3L3 activation, and thereby prevented RANKL-induced bone destruction, suggesting the inactivation of ER stress CREB3L3-induced signaling pathways may be of therapeutic use for the treatment of osteoporosis." (PMID 33743732, 2021).
alcoholic steatohepatitis (1 paper, 2016). "Surprisingly, LKO mice demonstrated increased liver injury and fibrosis in the absence of the excess hepatic lipid accumulation compared to floxed mice, indicating liver-specific deletion of Creb3l3 accelerates the development of non-alcoholic steatohepatitis." (PMID 27291420, 2016).
bladder cancer (1 paper, 2024). "According to previous studies, the genes of the CREB family behave differently, most of which have a tumor-suppressing nature like the gene CREB3L3, which is identified as a low-risk gene having high expression in the case of bladder cancer." (PMID 38638111, 2024).
gastric cancer (1 paper, 2024). A primary or metastatic malignant neoplasm involving the stomach. "It was also found that high expression of CREB3L3 helps in the bad prognosis of gastric cancer." (PMID 38638111, 2024).
gestational diabetes (1 paper, 2023). Carbohydrate intolerance first diagnosed during pregnancy. "We indicate that diet regulated gene expression of PPARα, NOS, CREB3L3, IRS, and CPT I, altering cellular physiological mechanisms and thus increasing or decreasing the risk of gestational diabetes." (PMID 37799768, 2023).
glioma (1 paper, 2023). A benign or malignant brain and spinal cord tumor that arises from glial cells (astrocytes, oligodendrocytes, ependymal cells). "Nomogram and calibration curves further confirmed that the prognostic model composed of SYT1, CREB3L3, ITPR1, RASGRF2, PDX1, and RASGRF1 has good stability and potential application value for poor prognosis in patients with glioma." (PMID 37090987, 2023). "The LASSO regression model was constructed to screen the molecular models related to glioma prognosis, which were composed of SYT1, CREB3L3, ITPR1, RASGRF2, PDX1, and RASGRF1." (PMID 37090987, 2023). "Interestingly, the imbalance of oxidative stress-related pathways was also exhibited in glioma tissues, and the expression of SYT1, CREB3L3, ITPR1, RASGRF1, RASGRF2, and PDX1 were significantly different from that of para-cancerous tissues." (PMID 37090987, 2023).
hepatitis virus B infection (1 paper, 2025). "More research is needed to elucidate the regulatory mechanisms of CREB3L3, particularly in the context of non-hepatitis-B-induced HCCs." (PMID 41301006, 2025).
lupus (1 paper, 2022). "Indeed, most Nr4a1-controlling genes (Grin1, Creb3l3, Mef2a, Mef2c, and Mef2d) were reduced in the lupus hippocampus, as revealed by sequencing assays." (PMID 35177587, 2022).
cancer (8 papers, 2021 to 2023). A tumor composed of atypical neoplastic, often pleomorphic cells that invade other tissues. "In GC, CREB3L3 is related to the OS derived from univariate and multivariate Cox regression analysis and is highly expressed in cancer tissues." (PMID 36936373, 2023). "CREB3L3, which was an ER stress-related transcription factor, had been proven to exert a tumor suppressor role in various cancers." (PMID 36120545, 2022). "Furthermore, qRT-PCR results from our specimens verified an over-expression of ASCL2, CREB3L3, and MFAP2 in the cancer cells compared with the normal cells." (PMID 36936373, 2023). "The results of UALCAN database analysis showed that the mRNA expression levels of CALR, CREB3L3, FBOX6, and KDELR3 were increased in cancer tissues compared with normal tissues, while the mRNA expression levels of CRYAB, DNAJB4, and HSPB6 were decreased in BLCA." (PMID 34930465, 2021).
metabolic disease (5 papers, 2016 to 2023). A congenital disorder (due to inherited enzyme abnormality) or acquired (due to failure of a metabolically important organ) disorder resulting from an abnormal metabolic process. "However, further studies are required to verify the intestinal function of CREB3L3 in models of metabolic disease such as those fed the MCD diet." (PMID 27291420, 2016).
tumor (4 papers, 2020 to 2024). "The expression level of these genes differs significantly between the tumor and normal tissues, but CREB3L3 and TRIB3, and XBP1 are overexpressed, while PPP1R15A is expressed conversely." (PMID 37880674, 2023).
CREB3L3 also shares sentences with these, for which no sentence is quoted: diabetes (5 papers); atherosclerosis (4); non-alcoholic steatohepatitis (4); Hyperglycemia (3); nonalcoholic fatty liver disease (3); colitis (2); Hypercholesterolemia (2); infection (2); liver fibrosis (2); anorectal malformation (1); breast carcinoma (1); digestive system carcinoma (1); endotoxemia (1); genetic disorder (1); inflammatory bowel disease (1); liver (1); liver diseases (1); nutritional deficiency (1); overnutrition (1); sarcoma (1); Shock (1).